CAV1 (caveolin 1)
Diseases named in the same sentence as CAV1 in open-access papers (continued):
Sharing a sentence is not in itself a finding about the gene and the disease.
invasive breast carcinoma (13 papers, 2007 to 2026). A carcinoma that infiltrates the breast parenchyma. "The previous genomic study has revealed that CAV1 gene mutation occurred in up to ∼16% of breast invasive carcinoma patients." (PMID 36147736, 2022). "A somatic missense mutation in CAV1 at codon 132, converting proline to leucine (P132L), has been detected in 11-16% of invasive breast cancer patients." (PMID 26315660, 2015). "In this study, CAV1 expression was significantly associated with a shorter BCSS in patients with low grade invasive breast cancers whereas patients with CAV2-positive cancers had a shorter DFS." (PMID 18612310, 2008). "In invasive breast cancer, the expression of Cav-1 in stromal cells is associated with tumor size, histological grade, and lymph node metastasis, so Cav-1 may be a clinical diagnostic indicator of tumor prognosis." (PMID 37828916, 2023). "It is controversial about the distribution of Cav-1 in normal and invasive breast cancer in recent studies." (PMID 30348118, 2018). "Caveolin-1 positivity was detected in 13.4% whereas CAV2 was found in 5.9% of invasive breast cancer cases." (PMID 18612310, 2008). "A significant increase in Caveolin-1 expression was observed comparing invasive breast cancer to both benign breast tissue and non-invasive breast cancer." (PMID 17915016, 2007). "We found Caveolin-1 expression in epithelial tumour cells in 32 of 109 cases (29.4%) of invasive breast carcinomas." (PMID 17915016, 2007). "In this study we demonstrated expression of Caveolin-1 in one third of invasive breast cancers." (PMID 17915016, 2007). "Moreover, there is evidence that CAV1 expression is inversely correlated with progression of ductal carcinoma in situ (DCIS) to invasive breast cancer and several recent studies highlighted the important role of the stroma surrounding DCIS in the progression to invasion." (PMID 20017941, 2009). "However, Caveolin-1 expression was found in 32 of 109 cases of invasive breast carcinomas (29.4%)." (PMID 17915016, 2007). "Thus, we observed Caveolin-1 expression in 32 of 109 cases of invasive breast carcinomas (29.4%)." (PMID 17915016, 2007). "Caveolin-1 expression could be determined in 109 of 200 cases of invasive breast cancers (54.5%)." (PMID 17915016, 2007). "Despite the controversy about the distribution of CAV1 and CAV2 in normal and invasive breast cancer, recent studies confirmed the preferential expression of both genes and their proteins in normal myoepithelial cells." (PMID 18612310, 2008). "Caveolin-1 and CAV2 protein expression was assessed on a tissue microarray containing 880 unselected invasive breast cancer cases, by means of immunohistochemistry." (PMID 18612310, 2008). "The aim of this study was to comprehensively examine expression of Caveolin-1 in different benign and malignant breast tissues, including DCIS and invasive breast cancer using tissue microarray (TMA) technology." (PMID 17915016, 2007). "However, luminal epithelial cells demonstrated Caveolin-1 expression in 13.4% of DCIS and 9.4% of invasive breast cancer specimens." (PMID 17915016, 2007). "Using tissue microarray (TMA) technology cases of invasive breast cancer, DCIS, benign breast disease (i.e. fibroadenoma, sclerosing adenosis, ductal hyperplasia and radial scar) and normal breast tissue were evaluated for Caveolin-1 expression." (PMID 17915016, 2007). "In order to examine the potential clinical relevance of Caveolin-1 in premalignant and malignant breast disease, we studied Caveolin-1 protein expression in tissue probes of healthy breast tissue, benign breast disease, DCIS, and invasive breast cancer, using immunohistochemistry." (PMID 17915016, 2007). "Caveolin-1 expression in invasive breast cancer could neither be correlated with survival parameters such as overall or disease-free survival nor with established clinical and pathological markers." (PMID 17915016, 2007).
invasive breast carcinoma (continued). "Correlation studies performed in the cases of invasive breast cancer showed that none of the clinical and pathological factors significantly correlated with Caveolin-1 expression, with the exception of positive correlation between Caveolin-1 expression and multifocality (p = 0.008)." (PMID 17915016, 2007). "In our immunohistochemical study, we found significant Caveolin-1 expression in one third of invasive breast carcinomas, whereas neither normal breast tissue, nor benign breast disease, nor DCIS showed relevant Caveolin-1 expression." (PMID 17915016, 2007).
Parkinson disease (13 papers, 2008 to 2024). A progressive degenerative disorder of the central nervous system characterized by loss of dopamine producing neurons in the substantia nigra and the presence of Lewy bodies in the substantia nigra and locus coeruleus. "This suggests that the expression of CaV1.342 and CaV1.342A remains robust throughout the degenerative process in the Parkinson’s disease model." (PMID 39770531, 2024). "This indicates that the expression of CaV1.342 and CaV1.342A is maintained at a robust level during the degenerative process in the parkinsonism model." (PMID 32009942, 2019). "Meanwhile, CMI provides a new paradigm to develop CaV1 inhibitors, the therapeutic potential of which is implied by computational modeling of CaV1.3 dysregulations related to Parkinson’s disease." (PMID 28059704, 2017). "Both CaV1 channels and neurite outgrowth are involved in a variety of neuropsychiatric and neurodegenerative diseases, such as autism, bipolar disorder, schizophrenia, Parkinson’s disease, and Alzheimer’s disease." (PMID 35589958, 2022). "Finally, we would like to mention that 25HC inhibits caveolin-1 expression and the subsequent Cav-1+-endossome-dependent IFN-γ signaling in the context of Parkinson’s disease, an aspect of the regulation of the inflammatory response not investigated so far in coronavirus infection." (PMID 38106410, 2023). "We used 1-methyl-4-phenyl-1,2,3,6-tetrahydropyridine (MPTP), a neurotoxin that induces Parkinson disease, to evaluate the change of midbrain structure and the behavior of the anti-inflammatory factor e-cadherin, interleukin-6, tyrosine hydroxylase, phosphatase and tensin homolog, and caveolin-1." (PMID 27194825, 2016). "Furthermore, this study shed light on the altered gene expression of CTNNB1, NDUFS6, and CAV1 in PBMC, which could serve as biomarkers for detecting pesticide-related Parkinson’s disease." (PMID 37508933, 2023). "Notably, the expression levels of CaM are downregulated in Parkinson’s disease and Alzheimer’s disease, for which the overall inhibitory effects of DCT peptides on CaV1 and CaV1-mediated downstream signals would be even more profound due to less apoCaM competition." (PMID 35589958, 2022).
systemic sclerosis (13 papers, 2010 to 2025). A chronic disorder, possibly autoimmune, marked by excessive production of collagen which results in hardening and thickening of body tissues. "One previously study found that rs959173-C allele was a protective allele and with a higher CAV1 protein level in systemic sclerosis patients." (PMID 28148898, 2017). "A previous study revealed that in addition to oxidative stress, increased serum levels of endothelin, a vasoconstricting peptide, and single nucleotide polymorphisms (SNPs) of caveolin 1, an inhibitor of tissue fibrosis, are associated with NC abnormalities in systemic sclerosis." (PMID 37874367, 2024). "CAV-1 is also expressed in immune cells; notably, aberrant CAV-1 expression was found in the monocytes of patients with systemic sclerosis and psoriasis and CAV-1 deficient monocytes are hypermigratory towards disease sites." (PMID 36532050, 2022). "In contrast to CAV1, little is known about the function of CAV2 although it has been implicated in type 2 diabetes mellitus, systemic sclerosis, cardiac conduction defects, cancer, and primary open angle glaucoma." (PMID 23667606, 2013). "In systemic sclerosis, caveolin-1 is thought to be anti-fibrotic by its effect on TGFβ signalling by receptor degradation; as a model of accelerated fibrosis, renal allograft failure has been associated with CAV1 SNP rs4730751 donor genotype." (PMID 23894397, 2013). "CAV1 is recognised as an inhibitor of both cell proliferation and fibrosis and is known to be dysregulated in fibrotic diseases such as systemic sclerosis, pulmonary fibrosis, fibrosing cardiomyopathy, and keloid formation." (PMID 23667606, 2013). "However, in several pathological conditions associated with increased fibrosis, such as systemic sclerosis, IL-6 can act as a profibrotic cytokine, suggesting the increase in collagen deposition observed in CAV1−/− adipose tissue could be related to the elevated levels of IL-6." (PMID 23049990, 2012). "Cav-1 is involved in the pathogenesis of systemic sclerosis (SSc)." (PMID 41030451, 2025).
chronic obstructive pulmonary disease (12 papers, 2017 to 2025). A chronic and progressive lung disorder characterized by the loss of elasticity of the bronchial tree and the air sacs, destruction of the air sacs wall, thickening of the bronchial wall, and mucous accumulation in the bronchial tree. "With the stimuli of CSE, Cav-1 also negatively regulates the autophagic label protein LC3B (autophagic protein microtubule-associated protein 1 light chain-3B) in COPD (chronic obstructive pulmonary disease) disease, thus protecting the epithelial cells from apoptosis and autophagy." (PMID 31901898, 2020). "However, some results are conflicting regarding the association between the Cav-1 polymorphisms and the risk of atrial fibrillation in cardiac arrhythmias." (PMID 28346478, 2017). "For instance, lower CAV1 levels in lung tissue were related to chronic obstructive pulmonary disease (COPD), while an abnormal white blood cell count was associated with higher CAV1 levels in various brain regions." (PMID 40332409, 2025). "Given that the over‐expression of Nos1ap per se has a detrimental effect on CaV1.2 conductance, our study suggests that targeting of the protein expression of Nos1ap could be a relevant future strategy for prevention of cardiac arrhythmia." (PMID 36352324, 2023). "Also, variants in CAV1, TRPM8, and BNP have been linked with PH secondary to chronic obstructive pulmonary disease." (PMID 33996849, 2021). "This study elucidates the pivotal role of the autophagic protein LC3B in mediating cigarette smoke-induced apoptosis and emphysema in chronic obstructive pulmonary disease (COPD), revealing its interaction with caveolin-1 and Fas, and suggesting novel therapeutic targets for COPD treatment." (PMID 40066166, 2025).
Cirrhosis (12 papers, 2009 to 2025). A chronic disorder of the liver in which liver tissue becomes scarred and is partially replaced by regenerative nodules and fibrotic tissue resulting in loss of liver function. "Mechanistic studies link Cav-1 dysregulation to diverse liver pathologies spanning cholestasis, viral hepatitis, cirrhosis, and hepatocellular carcinoma." (PMID 40430042, 2025). "Emerging evidence implicates Cav-1 in hepatic pathophysiology, with elevated expression observed in both clinical cirrhosis and experimental liver injury models." (PMID 40430042, 2025). "In fact, in cirrhosis, mechanical cues from the rigid matrix increase CAV1 activity in CAFs, promote caveolae formation, and facilitate secretion of tissue inhibitors of metalloproteinases (TIMP) to remodel the ECM." (PMID 40715090, 2025). "The upregulation of Cav1 has been observed in patients with cirrhosis and rats with bile duct ligation-induced cholestatic liver injury." (PMID 34434195, 2021). "Recent studies have reported that Cav1 plays a crucial role in liver function and the progression of hepatic diseases, including cholestasis, hepatitis, cirrhosis, and hepatocarcinogenesis." (PMID 34434195, 2021). "Caveolin-1 (CAV-1) is involved in hepatic sinusoidal angiogenesis and remodeling during progression to cirrhosis." (PMID 26317806, 2015). "We found also increased expression of caveolin-1 and caveolin-2 in blood in the group of patients with cirrhosis." (PMID 26317806, 2015). "There is evidence that DM patients had altered NO metabolism, and in a rat model of cirrhosis that over-expressed caveolin-1, the interaction with eNOS and both the basal and stimulated production of NO are depressed." (PMID 23840919, 2013). "The percentage of Caveolin-1 positivity was found extremely low in normal liver tissue (5%) while it was increased in cirrhosis (45%) and in HCC (66%) (p = 0.002 and p = 0.001 respectively)." (PMID 19239691, 2009). "In addition, the increased expression of CAV-1 was found in cirrhotic livers of patients infected with HCV; however, this finding is probably associated with higher cholesterol levels in cirrhosis." (PMID 36556936, 2022). "Similarly, Cav-1 was localized in liver sinusoidal endothelial cells (LSECs) of cirrhotic liver human samples, with an overexpression of Cav-1 in late-stage cirrhosis." (PMID 28970796, 2017). "In order to investigate Cav-1 expression in different stages of hepatocellular carcinogenesis, we analyzed its expression profile by immunoperoxidase staining of normal liver (n = 20), cirrhosis (n = 29), and HCC (n = 95) tissue samples." (PMID 19239691, 2009). "In this study, we aimed to identify the expression status of Cav-1 in normal, cirrhotic, and HCC tumor samples, in order to investigate the changes in Cav-1 expression during progression from normal liver to cirrhosis and HCC." (PMID 19239691, 2009). "Although there was an increase in phospho-CAV1 staining towards normal to cirrhosis and to HCC, this result was not statistically significant (p>0.05)." (PMID 25148256, 2014). "The immunoreactivity of both phospho-Met and phospho-CAV1 in the same liver tissue sample showed a similar staining pattern that was absent in normal liver tissues, present in cirrhosis and increased in HCC compared to normal and cirrhotic tissues." (PMID 25148256, 2014).
oral squamous cell carcinoma (12 papers, 2015 to 2025). "We investigated the clinicopathological significance of the expression of two caveolae component proteins, dynamin‐2 (DNM2) and caveolin‐1 (CAV1), in primary tumors of patients with oral squamous cell carcinoma (OSCC)." (PMID 40419438, 2025). "Univariate and multivariate analyses of clinicopathological factors and the expression and aspects of DNM2 and CAV1 in relation to overall survival in patients with oral squamous cell carcinoma (n = 80)." (PMID 40419438, 2025). "As an example, the caveolae protein caveolin-1 (CAV1) has been found to modulate the metastatic and invasive capabilities of oral squamous cell carcinoma (OSCC) cells." (PMID 37568764, 2023). "There are few studies describing caveolin-1 expression in tumors arising intraorally or within the gnathic bones, such as primordial odontogenic tumors, malignant salivary gland tumors, oral squamous cell carcinoma and potentially malignant oral lesions." (PMID 33037799, 2021). "Our goal was to shed light on the expression of the two different isoforms of Cav-1 in normal fibroblasts (NFs) and CAFs of patients with oral squamous cell carcinoma (OSCC)." (PMID 33774714, 2021). "CD63 and caveolin 1 (CAV1) expressing exosomes were analyzed in stage IV oral squamous cell carcinoma (OSCC) patients." (PMID 32759810, 2020). "In oral tumors, caveolin-1 has been studied mainly in oral squamous cell carcinoma (OSCC) and its carcinogenesis and tumor progression processes, and caveolin-1 exhibits increased immunoexpression in OSCC compared to normal mucosa, dysplastic lesions and oral lichen planus." (PMID 33037799, 2021). "We also detected the expression of CAV1, FTH1, and SLC3A2 in a normal oral epithelial cell line (NOK) and an oral squamous cell carcinoma epithelial cell line (HN6)." (PMID 39286654, 2024). "Our pilot study wanted to analyse the relationships between the plasmatic exosome levels, positive for either CD63 or CAV-1, in patients with stage 4 oral squamous cell carcinoma without distant metastasis or local bone invasion, before and after surgical treatment." (PMID 30917536, 2019).
sarcoma (12 papers, 2002 to 2023). A usually aggressive malignant neoplasm of the soft tissue or bone. "Although caveolin-1 is known to act as a tumor suppressor in cases of pulmonary adenocarcinomas and sarcomas, several recent studies found that caveolin-1 overexpression was associated with invasion and angiogenesis." (PMID 32676485, 2020). "In fact, a tumor suppressor role for CAV1 has been clearly demonstrated in several types of cancer including sarcomas." (PMID 25313138, 2014). "Testing for the expression of CAV1 in several sarcoma cell lines we found that its expression in most alveolar rhabdomyosarcoma cells was very low or undetectable." (PMID 25313138, 2014). "In contrast to other sarcomas, CAV1 has been suggested to be a marker of poor differentiation for rhabdomyosarcomas associating its expression to a better prognostic entity." (PMID 21471610, 2011). "In those sarcomas where CAV1 was demonstrated to act as a tumor suppressor, targeted ectopic re-expression or introduction of a CSD would be a feasible option." (PMID 21471610, 2011). "In epithelial tumors the role of CAV1 in sarcomas is very contradictory; this is aggravated by the fact that functional studies are very scarce." (PMID 21471610, 2011). "Depending on the role assigned to CAV1 in every sarcoma type it will be possible to use different targeting options." (PMID 21471610, 2011). "Caveolin-1 reportedly functions as a tumor suppressor in sarcomas." (PMID 36497311, 2022). "Interestingly, we have observed high expression of CAV1 in some cell lines representative of these sarcomas, such as leiomyosarcoma and synovial sarcoma." (PMID 21471610, 2011). "However, ambiguous roles have been ascribed to caveolin-1 in signal transduction and cancer, including sarcomas." (PMID 21471610, 2011). "In addition, as more protein and signaling molecules are found to interact with and regulate CAV1 expression the design of novel therapies for sarcomas will evolve." (PMID 21471610, 2011). "However, the development of new reagents such as siRNAs, peptide and small-molecule inhibitors will define new avenues for therapies, not only for some sarcomas but for tumors that present CAV1-triggered progression." (PMID 21471610, 2011). "Therefore it was concluded that CAV1 is a candidate tumor suppressor gene in sarcomas." (PMID 21471610, 2011).